TNF (tumor necrosis factor)
Diseases named in the same sentence as TNF in open-access papers (continued):
Sharing a sentence is not in itself a finding about the gene and the disease.
encephalitis (continued). "Of these, the negative association of IL-15 with Qalb is a novel finding as, to our knowledge, IL-15 has not been studied in viral encephalitis before, but it can be interpreted in a framework of the upregulated TNFα-dependent response." (PMID 40003967, 2025). "In encephalitis patients, the levels of inflammatory cytokines, such as IFN-b, IFN-g, IL-3, and TNF-a, were directly correlated with levels of the previously listed bacteria and could reflect disease severity." (PMID 38259358, 2023). "In addition, LGI1 encephalitis patients with brain MRI abnormalities presented the elevated level of PDL2 and CCL2 but lower levels of TNFα (all p < 0.05) in serum." (PMID 37644514, 2023). "We detected higher levels of TNF-α, IL-10 and GM-CSF in CSF of paraneoplastic anti-NMDARE patients compared to the negative symptom control group (P < 0.05)and lower level of IL-1α and VEGF-A compared to the anti-NMDAR encephalitis patients(P < 0.05)." (PMID 32771066, 2020). "In earlier reports, levels of IL-1β, IL-6 and TNFα were found to be significantly elevated in fatal EV-A71 patients with encephalitis and pulmonary oedema, when compared to patients with no complications." (PMID 32123257, 2020). "However, during WNV encephalitis, PLX5622 treatment also significantly decreased transcriptional expression of both TNF and IFNβ." (PMID 30704498, 2019). "TNFα was detectable and tended to be elevated in most of the meningitis/encephalitis serum samples, significantly in the non-TBE group (p < 0.05) but the increase in comparison with controls in the TBE group was not significant (p = 0.063)." (PMID 28646884, 2017). "The data confirmed the expected correlation of TNF-expression, severe encephalitis and microglia activation but did apparently not change the percentage of perivascular microglia/macrophages in the total count of invading immune cells." (PMID 22848506, 2012). "The present data also showed the increased expression of Tlr3 along with TNF-α at an early phase of JEV infection and it may be involved in virus entry and resultant encephalitis." (PMID 21371334, 2011). "While TNFR1 seems to play a relevant role in control of viral replication in the CNS when HSV-1 is inoculated by the intracranial route, TNF-α seems to protect against encephalitis by a mechanism independent of TNFR1 when HSV-1 is inoculated in the periphery." (PMID 21388530, 2011). "Anti-TNF treatment did not improve the CNS symptoms of these patients, who may have suffered from viral encephalitis." (PMID 41608123, 2025). "In particular, it has been found that interleukin 6 (IL-6) and tumor necrosis factor (TNF)-alpha are increased in severe cases of ANE, showing the significance of the inflammatory reaction in the pathogenesis of the brain damage typical in these types of encephalitis." (PMID 40757726, 2024). "Previous studies have found that IL-6, IL-1β, IL-8, tumor necrosis factor-alpha (TNF-α), monocyte chemotactic protein-1 (MCP-1), and granulocyte-macrophage colony-stimulating factor (GM-CSF) was highly elevated either in serum or CSF of patients with COVID-19 related encephalitis." (PMID 37384050, 2023). "However, the roles of CCR2 and TNF-α should be validated by using more doses and the modified treatment schedule, while this study showed that the blockade of both CCR2 and TNF-α could partially inhibit the polarization of M1 macrophages, which therefore may reduce encephalitis incidences." (PMID 34831405, 2021). "The analysis showed that there was a statistically significant correlation of CSF cell-free mtDNA with IL-6 (r = 0.307, p = 0.041), but neither with IL-10 (r = −0.085, p = 0.319) nor TNF-α (r = −0.050, p = 0.391) in the acute stage of anti-NMDAR encephalitis." (PMID 30792710, 2019).
encephalitis (continued). "In addition, blood eosinophil leukocyte chemotactic factor, IFN-γ, IL-15, IL-6, interferon gamma-induced protein-10, and tumor necrosis factor-α were significantly elevated before disease deterioration in a non-fatal encephalitis SFTS patient, which may be due to encephalitis development." (PMID 36406394, 2022).
lung adenocarcinoma (89 papers, 2004 to 2026). A carcinoma that arises from the lung and is characterized by the presence of malignant glandular epithelial cells. "This study investigated the molecular mechanisms associated with PRFR on cell survival and metastasis of TNF-α-induced A549 human lung adenocarcinoma." (PMID 31540489, 2019). "Taken together the loss of Stat1 leads to an impaired TNFα mediated immune signaling, resulting in a complete defect to kill tumor cells in our murine model of lung adenocarcinoma." (PMID 30647851, 2018). "We previously reported that cardamonin, a chalcone-type flavonoid, inhibited TNF-α-induced ICAM-1 expression in human lung adenocarcinoma A549 cells." (PMID 41302385, 2025). "For Instance, the E2 enzyme UBE2T inhibited CD8+ T-cell infiltration and expression of immune-promoting factors (IFN-γ, TNF-α and IL-2) in lung adenocarcinoma by activating the glycolytic pathway upon binding to FOXA1." (PMID 40183093, 2025). "Subsequent studies found that the downregulation of α5 nAChR significantly increased TNF-α expression and the phagocytosis of macrophages in lung adenocarcinoma." (PMID 38921563, 2024). "The recent trial of TNF-α inhibitor certolizumab plus chemotherapy in stage IV lung adenocarcinomas is notable for targeting cancer-induced inflammation involving tumor-produced IRFs." (PMID 39206193, 2024). "In 2014, a study showed that the dose-dependent synergic effect of TNF-α and CB significantly induced apoptosis in the human lung adenocarcinoma cell A549." (PMID 38895635, 2024). "In other word, in patients with lung adenocarcinoma, the expression of TNF-α and IFN-γ decreased with the upregulation of Tim-3 expression." (PMID 36865498, 2023). "A parallel investigation demonstrated that TRPA1 expression on the plasma membrane of human lung adenocarcinoma A549 cells can be increased by inflammatory cytokines, such as interleukin (IL)-1α, IL-1β, and tumor necrosis factor α (TNFα)." (PMID 37174661, 2023). "In the present study, we found that cucurbitacin B reduced the level of ICAM-1 expression induced by TNF-α and IL-1α in human lung adenocarcinoma A549 cells." (PMID 35806134, 2022). "As a novelty, we used tumor oligopeptides typical of lung adenocarcinoma and TNF-α stimulation on the 6th day of incubation." (PMID 35589776, 2022). "In lung adenocarcinoma model, IL-33 can activate NK in a TNF-α-dependent manner through activating the NF-κB signaling pathway, and promoting the proliferation and activation of CD8+ T cells, consequently inhibiting tumor metastasis." (PMID 35634336, 2022). "In the present study, we found that cucurbitacin B decreased the expression of ICAM-1 in human lung adenocarcinoma A549 cells stimulated with TNF-α or interleukin-1α." (PMID 35806134, 2022). "An in vitro study that used clinically relevant concentrations of lidocaine and ropivacaine demonstrated that local anesthetic agents inhibit TNF-α-induced invasion of lung adenocarcinoma by blocking the activation of Akt and focal adhesion kinase." (PMID 35898583, 2022). "In a subsequent study, the same group showed that lidocaine-related inhibition of TNFα-induced, Src-dependent signalling in lung adenocarcinoma cells resulted in reduced MMP-9 expression and reduced cancer cell invasion." (PMID 34408981, 2021). "IL-1β and TNFα were shown to downregulate 15-PGDH expression in A549 human lung adenocarcinoma cells with concomitant induced COX-2 expression." (PMID 33596205, 2021). "The upregulated metabolite glutamine was found to inhibit the migration of human lung adenocarcinoma A549 cells, possibly by downregulating the expression of TNF-α and NF-ΚB p65 protein." (PMID 34306147, 2021). "The aim of this study was to investigate the anti-inflammatory and anti-proliferative effects of NCS 613, a specific PDE4 inhibitor, on TNFα-treated human lung adenocarcinoma cell line (A549) and on human lung adenocarcinoma explants." (PMID 32973507, 2020).
lung adenocarcinoma (continued). "TNF expression has demonstrated potent inhibitory activity of SP-B in a human lung adenocarcinoma cell line and decreased surfactant protein-A (SP-A) expression in lung epithelial cells through the p38/MAPK pathway." (PMID 33537342, 2020). "WNT10A, PDGFA, TNF, and NRG1 had been identified as important paracrine factors from infiltrated dendritic cells to regulate neuropathic pain associated with lung adenocarcinoma." (PMID 32434423, 2020). "Subsequently, it is verified that 9 core targets for ginseng treatment of lung adenocarcinoma, namely, JUN, IL-1β, IL-2, ICAM1, HMOX1, MMP9, MMP2, PTGS2, and TNF, are closely related to the proliferation, migration, and apoptosis of lung adenocarcinoma cells." (PMID 32802118, 2020). "The present study was designed to investigate the effect of dicentrine on the enhancement of TNF-α-induced A549 lung adenocarcinoma cell death and to investigate the role of dicentrine as a potent inhibitor of TNF-α-induced cell invasion." (PMID 31766230, 2019). "This study was the first to report that PRFR sensitized A549 lung adenocarcinoma cells to TNF-α-induced cell death." (PMID 31540489, 2019). "In the present study, we demonstrated that quinacrine decreased the expression of intercellular adhesion molecule-1 (ICAM-1) induced by tumor necrosis factor (TNF)-α and interleukin-1 (IL-1) α in human lung adenocarcinoma A549 cells." (PMID 29207489, 2017). "In the course of our screening, quinacrine was initially found to inhibit the expression of intercellular adhesion molecule-1 (ICAM-1) in response to TNF-α in human lung adenocarcinoma A549 cells." (PMID 29207489, 2017). "Although it has been reported that TNF-α decreases lung adenocarcinoma cell death and promotes angiogenesis and invasion, there is a positive correlation between the TNF-α levels and the chemoresponse." (PMID 27445423, 2016). "To evaluate these observations in vivo, we chose to analyze the progression of human lung adenocarcinoma A549 xenografts on co-treatment with TNF-α and BCG." (PMID 25208737, 2014). "In human lung adenocarcinoma cells, the tumor-promoting TPA and the tumor necrosis factor-alpha (TNF-α) were implicated in the stimulation of the expression of the mitochondrial manganese-dependent isoform of SOD (MnSOD) mediated by the Nox enzyme pathway." (PMID 23109817, 2012). "In this study, we show that in the GSEA analysis of TCGA lung adenocarcinoma RNA-seq data, the KEAP1 mutations in R320 and R470 were associated with enhanced Tumor Necrosis Factor alpha (TNFα) – Nuclear Factor kappa subunit B (NFκB) signaling as well as MYC and MTORC1 pathways." (PMID 38184997, 2024). "However, in the present study, we demonstrated that alantolactone selectively down-regulated the expression of tumor necrosis factor (TNF) receptor 1 (TNF-R1) in human lung adenocarcinoma A549 cells." (PMID 38675685, 2024). "More recent studies utilizing cyclic mechanical stretch on A549 lung adenocarcinoma cell lines revealed that cells activate Wnt/β-catenin and tumor necrosis factor-alpha (TNF-α) inflammation pathways in response to this mechanical stimulus, leading to an increase in cell invasion after stretching." (PMID 38605886, 2024). "Whether the high expression of Tim-3 in lung adenocarcinoma can inhibit the expression of TNF-α and IFN-γ through signal transduction or regulation of translation remains to be further explored." (PMID 36865498, 2023). "We found that an inflammatory signature and cytolytic T cell score correlate with increasing ENPP2 expression in human lung adenocarcinoma patients, which is in line with findings in the literature that inflammatory cytokines like IL-1β, TNF-α, and IFN-γ can promote ATX expression." (PMID 37655662, 2023). "LINC00968 inhibits the proliferation, migration and invasion of lung adenocarcinoma Our study identified the prognostic lncRNAs that TNF-related might target, thereby providing novel insight into their potential roles in the progression of GBM." (PMID 37153654, 2023).
lung adenocarcinoma (continued). "Using the lung adenocarcinoma cell line A549 in a test model, researchers showed that the RA-rich fraction of perilla seed meal exerts an antioxidant effect by scavenging tumor necrosis factor (TNF)-α-induced reactive oxygen species." (PMID 37834377, 2023). "In addition, a signature consisting of 11 cytokine genes in the lung environment is able to predict lymph node metastasis and prognosis of lung adenocarcinoma based on IL-8 and TNFα as the top two genes for predicting prognosis." (PMID 36425070, 2022). "Another in vitro study that used lidocaine, ropivacaine, and chloroprocaine demonstrated that amide-linked local anesthetic agents inhibited TNF-α-induced Src-activation and ICAM-1 phosphorylation, which are important in the migration of lung adenocarcinoma cells." (PMID 35898583, 2022). "Our phase I study examining the addition of certolizumab, an anti-TNF-α monoclonal antibody, to cisplatin and pemetrexed chemotherapy in patients with untreated stage IV lung adenocarcinoma demonstrated that this intervention is feasible, well-tolerated, and has a promising efficacy signal." (PMID 36241629, 2022). "Therefore, TNF-α-mediated lung inflammation can upregulate SOD2 expression in lung adenocarcinoma, and macrophages contribute to SOD2 upregulation by secreting TNF-α." (PMID 34777635, 2021). "Similarly, the induction of EMT in the A549 lung adenocarcinoma cell line using TGF-β/TNF-α led to a high increase in GABARAPL1 expression mediated by the EMT-related transcription factors of the SMAD family, whereas the other ATG8 genes were less modified." (PMID 34681055, 2021). "Moreover, amongst the ATG8 family, GABARAPL1 expression presented the greatest increase in expression during TGF-β/TNF-α-induced EMT in A549 lung adenocarcinoma cells." (PMID 34681055, 2021). "Indeed, it was recently described that TNF is one of the co-occurring frequently altered immune genes found within the TCGA pan-cancer lung adenocarcinoma (LUAD) dataset (n = 507)." (PMID 34445397, 2021). "Thus, a reduced expression of IL-1β, TNF-α, and IL-6 and an enhanced expression of IL-10 were observed in lung adenocarcinoma in mice treated with zotarolimus combined with 5-FU." (PMID 33925400, 2021). "To further underpin the links between KIAA1522 and TNFα-NFκB signaling and cisplatin responsiveness by clinical evidences, we performed integrative analyses using transcriptome profiles of lung adenocarcinoma patients from multiple cohorts, including single cell transcriptome studies." (PMID 32854746, 2020). "Therefore, we investigated the effects of dicentrine on TNF-α-induced tumor progression in A549 lung adenocarcinoma cells." (PMID 31766230, 2019). "In addition, TNF-α and interleukin-1β (IL-1β) induced pS-EphA2 in human lung adenocarcinoma A549 cells." (PMID 26158630, 2015). "Analysis of the therapeutic effects in different kind of diseases showed that the response rate for NSCLC of the trial group was 8/17 (47.06%), higher than that of the control group 1/6 (16.67%), which also means that TNFα has suppressive effects on lung adenocarcinoma." (PMID 15485573, 2004). "CASP4 enhances the expression of genes associated with angiogenesis and cell migration in lung adenocarcinoma cell lines through nuclear factor kappa-light chain-enhancer of activated B cell signaling without stimulation by lipopolysaccharide or tumor necrosis factor." (PMID 38849594, 2024). "TNF-α could upregulate MnSOD expression in A549 lung adenocarcinoma cells." (PMID 34833849, 2021). "Thus, the expression of IL-1β and TNF-α in mice treated with zotarolimus combined with 5-FU could be largely suppressed in lung adenocarcinoma." (PMID 33925400, 2021). "Further analysis of The Cancer Genome Atlas (TCGA) database showed that the mRNA level of TNF-α, a key cytokine responsible for NF-κB activation, was inversely correlated with GPRC5A expression in lung adenocarcinoma (LUAD)." (PMID 36413416, 2023).